ERVE-1 (endogenous retrovirus group E member 1)
Synonyms: HERV-E1; HERVE1; TCONS_00025599; formerly ERVE1
Gene: Long non-coding RNA gene on chromosome 17 (28,230,561 to 28,238,670, reverse strand). Ensembl gene ENSG00000267259.
Diseases named in the same sentence as ERVE-1 in open-access papers:
ERVE-1 is named in the same sentence as 4 diseases in open-access papers, as found by Europe PMC text mining. Sharing a sentence is not in itself a finding about the gene and the disease. The quoted sentences say what the papers report.
ovarian carcinoma (2 papers, 2021). A malignant neoplasm originating from the surface ovarian epithelium. "Expression of ERVE-1 env gene, the only full-length HERVE member, was observed in ovarian cancer and prostate cancer." (PMID 33996550, 2021).
ERVE-1 also shares sentences with these, for which no sentence is quoted: endometrial carcinoma (1 paper); prostate carcinoma (1); tumor (1).